CCR7 (C-C motif chemokine receptor 7)
Diseases named in the same sentence as CCR7 in open-access papers (continued):
Sharing a sentence is not in itself a finding about the gene and the disease.
infection (continued). "At later time points during infection, HSV-2 further downregulates chemokine receptor expression of CCR7, recognizing the lymphoid tissue expressed chemokine CCL19." (PMID 31963276, 2020). "The generation of CD83+ and CCR7+ DCs (Mt-MoDCs) requires the infection of monocytes with live MTB, since infection with heat-killed bacteria partially abrogates the effects on monocyte differentiation." (PMID 30650615, 2019). "There were also two DC related genes that showed significant difference between O1 and O2 (FLT3 and CCR7); these were downregulated following both APEC O1-GFP and APEC O2-GFP infection, but to a greater extent in the APEC O2-GFP infected cells." (PMID 31998322, 2019). "Differentiated CTLs downregulate their lymph node homing receptor CCR7 and upregulate CCR4 and CXCR3 for the migration to the site of infection." (PMID 30042762, 2018). "Downregulation of CCR7 and CD45RA on a subset of CD4+ and CD8+ T cells was detectable in the blood and spleen of NRG-HIS mice upon YFV-17D infection, indicating that the engrafted HIS responded to the infection." (PMID 30487575, 2018). "Three days after infection with Ad.EGFP, Ad.CCR7, Ad.BTLA, or Ad.CCR7 + BTLA, the cellular morphology of imDCs was examined under SEM." (PMID 28393074, 2017). "After infection with ECTV, cells from both mouse strains exhibited reduced percentage of CCR1+ and CCR7+ cells and decreased expression of CCR5, compared to mock-infected cells." (PMID 29312229, 2017). "The spleens of αβR−/− and αβR−/− λR−/− mice exhibited an increase in the levels of CCR7− CD62L− CD4+ and CD8+ T cells upon infection." (PMID 28811340, 2017). "Our results showed that the majority of chemokines and receptors were up-regulated more strongly in the CVS-11 infection than the HEP-Flury at a later stage, besides CCL22, CXCR3, CXCR6, and CCR7." (PMID 27242764, 2016). "Relative to HIV-negative donors, HIV-infected subjects had a significantly larger memory (non-CCR7+CD45RO-) CD8+ T cell pool in both the acute and chronic phases of infection." (PMID 27486665, 2016). "CCR7, Foxo1 and Foxo3a are also known transcriptional targets of Foxo1 or Foxo1 plus KLF2, and their mRNA levels remained unchanged during productive infection." (PMID 25330112, 2014). "To study the potential of NK cells to migrate to infected peripheral tissues upon MPXV infection, we assessed the expression of chemokine receptors CXCR3, CCR5, CCR6, and CCR7 on each NK cell subset." (PMID 24147080, 2013). "In an infection with viral or bacterial agents, which require a host immune response dominated by cytotoxic CD8+ T cells for clearance of the pathogen, CCR7-/- mice display a delayed, but ultimately protective response." (PMID 24205367, 2013). "For the first time in an infection model, we have shown that the majority of CCR2+ monocytes in the footpads of B6.WT mice also express CCR7." (PMID 24205367, 2013). "We observed an increased expression of CCR7 and CD103 on lung DC after infection, as well as MHC-II." (PMID 21611175, 2011). "We also evaluated replicate samples to investigate if the profile of CCR7 mRNA and protein expression correlated with the ability of MDDC to migrate to a CCL19 concentration gradient, measured 48 h post-infection (n = 5 donors)." (PMID 21731495, 2011). "From this systematic analysis, we identified a novel donor peripheral TSCM-like regulatory subset (PD-1+CD8+CD45RA+CCR7+) which was significantly positively correlated with alleviated aGVHD and lower infection in recipients." (PMID 40175340, 2025). "Altogether, PD-1+CD8+CD45RA+CCR7+ T cells have unique TSCM expression markers and possess features of both regulatory and effector T cells, and they correlate with ameliorated aGVHD and anti-infection in post allo-HSCT patients." (PMID 40175340, 2025). "Given that the analysis of DC transmigration occurred after an 18 h incubation, these results indicate that deletion of TgWIP does not modulate CCR7 post 18 h infection in vitro." (PMID 38977495, 2024).
infection (continued). "However, during infection, the proportion of iMOs increased in the blood of both Ccr2−/− RFP and Ccr7−/− mice at a similar rate to HET mice, but with only approximately half the magnitude." (PMID 38658802, 2024). "From the reduced accumulation of rpoB-H445Y Mtb in the DLNs early in infection and the decreased chemotactic sensitivity of infected BMDCs to CCL19, DCs infected with rpoB-H445Y Mtb likely have diminished expression of the cognate receptor, CCR7." (PMID 37682004, 2023). "On the other hand, the expressions of CCR7 and CXCR4 were significantly induced by WT infection." (PMID 37513744, 2023). "Higher expression of CCR7 on NK cells, a receptor for homing to lymphoid tissues, has been described during the early phase of infection but not during the later stages of infection." (PMID 35851334, 2022). "Although we did observe a decrease in the expression of the inhibitory marker PD-1 and an increase in the expression of the homing markers CXCR4 and CCR7 on MuV-specific CD8+ T cells over time, it is difficult to interpret the exact role of these markers in the memory phase after an acute infection." (PMID 34960178, 2021). "The expression of both CCR7 and CXCR4 increased significantly between 1.5 and 9 months post-infection for T cells specific for all three epitopes (p = 0.0002 and p = 0.0137, respectively), while the expression of CXCR3 remained stable between these two timepoints." (PMID 34960178, 2021). "In contrast, the frequencies of CD3+TCRαβ−CCR7+ and CD3+TCRαβ+CCR7+ MDMs were higher than that of CD3−CCR7+ MDMs (asterisks), and CCL19 levels (ligand to CCR7) were not modified as a result of H37Ra and H37Rv infection." (PMID 35008755, 2021). "Instead, transcripts for CCR7, the receptor for CCL19 and CCL21, were significantly lower in males compared to females in the late stage of HN878 infection, indicating reduced recruitment of DCs and/or T cells to the site of infection." (PMID 32198367, 2020). "However, later during infection, HSV-1 and HSV-2 also hamper CCR7 expression as an additional counterstrike for delaying mDC migration toward the SLO-expressed chemokine CCL19." (PMID 31963276, 2020). "The lack of in vivo activated CCR7+ pDC suggests that—at this stage of infection—only cDC migrate from infection sites to the lymph nodes." (PMID 32733474, 2020). "While susceptibility of CCR7-deficient mice to low-dose H37Rv infection was not increased, CCR7 knockout mice died significantly earlier than WT mice after infection with a higher inoculum of H37Rv31." (PMID 32198367, 2020). "For example, CCR7 upregulation was restricted to cDC in the lymph nodes after in vivo infection, but was observed in vitro in blood pDC irrespective of the TLR ligand used for stimulation." (PMID 32733474, 2020). "This hypothesis is further strengthened by the observation that decreased migration capability occurred already 4 hpi, while the chemokine receptor CCR7, mediating CCL19-directed migration, was downregulated at later time points post infection." (PMID 31963276, 2020). "Infection with the S. aureus USA300 WT or the S. aureus Δαβδ mutant strain induced the up-regulation of MHCII, CD86, CCR7, CD80, CD40, and PD-L2 on all DC subsets in the spleen starting 6 h pi compared to PBS-treated mice as analyzed by flow cytometry staining." (PMID 31134074, 2019). "These top genes included IFITM1 and IFITM2, which were significantly expressed between the acute and post-acute visit, but not between infants with severe versus mild infection, and CCR7, which has been found to be downregulated in RSV patients." (PMID 31554845, 2019). "Virus-specific CD8+ effector T cells play a critical role in eliminating HIV-1, EBV, HBV, CMV and HCV infections, and the expression patterns of CCR7, CD27, and CD28 exhibit similar characteristics during the primary infection phase and chronic phase of a persistent infection." (PMID 31632965, 2019).
infection (continued). "Expression of Cd3d, Cd8a, Ifn, Ccl5 and Tbx21 remained highly upregulated 56 days post-infection whereas Ccr7 did not." (PMID 29040326, 2017). "On the other hand, S. mansoni treated hMDMs expressed higher levels of CCR7 (M1 macrophages;), produced less IL-10 during infection, showed no elevation in CCL22 and were also more fit to control Mtb." (PMID 28192437, 2017). "Whilst we did not detect any changes in CCR7 gene expression in this early infection, gene expression of CXCR4 was downregulated." (PMID 28572564, 2017). "Tfh isolated from the mediastinal LN 9 days after infection exhibited heightened Bcl6 expression along with decreased CCR7 (e respectively) relative to the NonTfh population." (PMID 27329272, 2016). "Unexpectedly, although infection of DCs by DV up-regulated expression of CCR7, this effect was not affected in flow cytometry analysis of DCs deficient in Gal-9." (PMID 25754930, 2015). "To assess the role of dendritic cells for the early colonization dynamics with S. Tm we conducted infection experiments in mice lacking CCR7, in which dendritic cell movement is impaired." (PMID 24068916, 2013). "Due to the reciprocal developmental pathway, Th17 cells (CD4+IL-17+) were also analysed, and an increased percentage was seen only at day 28 after infection in B6.CCR7-/- mice (data not shown)." (PMID 24205367, 2013). "However, the CCR7-expressing cells in CD56+ and DP population were markedly reduced (p<0.01) upon MPXV infection, a result consistent with that from blood NK cells." (PMID 24147080, 2013). "MPXV infection did not induce a distinguishable change on CCR7 expression in other three NK populations that were negative at steady state and during MPXV infection." (PMID 24147080, 2013). "Chemokine receptor analysis revealed reduced expression of CXCR3, CCR7, and CCR6 on NK cells at early time points (days 2 and 4 after virus inoculation), followed by an increased expression of CXCR3 and CCR5 at later time points (days 7-8) of infection." (PMID 24147080, 2013). "Moreover, we indicated nDens of 2 genes induced and 2 genes repressed in all infection performed and nDens of all genes discussed above (IL-1β, IL-6, IL-12, TNF-α, IL-10, ADAM19, CCR7, CCL20 and IL-18)." (PMID 21436989, 2011). "Moreover, CCR7 induction in EBV-infected cells was recurrently proposed to enable homing of lymphoid cells to secondary lymphoid tissue, where the virus in turn propagates infection or establishes latency, thereby driving lymphomagenesis." (PMID 34039950, 2021). "Interestingly, we do find that PRE cells express significantly lower levels of CCR7 than both total Tm cells and HIV-infected cells, suggesting that HIV selects CCR7low cells for infection, but then as part of remodeling upregulates expression of this homing receptor." (PMID 32452381, 2020). "However, this decrease in CCR7 expression was transient, as the MFI and percentage of CCR7+ DCs in the MLN was not different between the two groups prior to infection or 3 days after infection." (PMID 30412605, 2018). "We further examined the gene expression of pro-inflammatory chemokines (CXCL1, CXCL2 and CCL2), chemokine receptor CCR7, and TLR4 in lung tissues in order to determine the potential mechanism(s) of immune cells infiltration into the lungs of newborns following low dose infection with B. pertussis." (PMID 28798335, 2017). "Importantly, in these immunosuppressed patients, CCR7+ KIR+ NK cells could also provide a rapid and more efficient line of defense against life-threatening infections." (PMID 27774094, 2016). "Therefore, levels of CXCR3 (receptor for CXCL9 and CXCL10), CXCR5 (receptor for CXCL13), CCR5 (receptor for CCL3 and CCL5), and CCR7 (receptor for CCL19) were analyzed on CD45hiCD11bloCD19+ B cells which infiltrated the brain at 7, 14, 30, and 60 days post infection." (PMID 27207308, 2016).
infection (continued). "Interestingly, and not in contraposition, infection of DCs by T. gondii leads to an up-regulation of CCR7 and down-regulation of CCR5, and also up-regulation of co-stimulatory molecules and cell surface maturation markers." (PMID 26406763, 2015). "We next tested whether infection of skin DCs was likely to have an impact on their capacity to migrate towards the chemokine CCL19, which is expressed in the T cell zones of LN follicles to attract CCR7-expessing migratory cells." (PMID 25474532, 2014). "However, an analysis of the function of this receptor in complex infection models shows that there is tolerance, allowing cell migration in the absence of CCR7 under inflammatory conditions." (PMID 24205367, 2013). "Infection with both low and high virulence isolates resulted in down-regulation of mRNA levels for chemokines CCL2, CCL3L, CXCL2 and chemokine receptors CCR1, CCR5, CXCR3, CXCR4 and up-regulation in expression of mRNAs for CCL4, CXCL10 and chemokine receptor CCR7." (PMID 23265239, 2013). "Thus, whereas robust infection with HMPV and HPIV3 stimulated expression of CCR7, robust infection with HRSV did not." (PMID 21731495, 2011). "Thus, while the balance between the chemokines CCL21 and CCL3 changes during infection, the receptors for these chemokines, CCR7 and CCR5 respectively, are not altered on the naive T cells in the absence of cognate antigen." (PMID 19578440, 2009). "Notably, the genes induced by the infection were enriched in multiple immune activation pathways, including cytokine-cytokine receptor interaction (e.g., Il22, Tnfrsf9 and Clcf1), JAK-STAT signaling pathway (e.g., Stat3), and chemokine signaling pathway (e.g., Ccr7) 33–35." (PMID 39013884, 2024). "Based on the unaffected CCR7 surface expression at 4 hpi we hypothesized that distinct mechanism(s), apart from solely downregulating the respective chemokine receptor CCR7, account for the HSV-mediated inhibition of mDC transwell migration at this early time point post infection." (PMID 31963276, 2020). "Finally, CCR5 expression, observed in about 20% of M. tb-specific TSCM, suggests that at least some M. tb-specific TSCM may have the potential to migrate to sites of infection and are not confined to the lymphoid compartment, despite CCR7 expression." (PMID 29545791, 2018). "Irrespective of the participants’ infection history, DENV-specific CD8+ T cells were predominantly composed of the Temra subset (CCR7+CD45RA+)." (PMID 39989460, 2025). "Although high expression of CCR7 and CD62L enables Tcm cells to preferably localize to lymphoid tissues, lack of CCR7 and CD62L expression promotes Tem cells to take up residence in nonlymphoid tissues where they can be rapidly mobilized to sites of infection." (PMID 37582972, 2023). "Of note, the increase in TSCM cell enrichment was accompanied by an enrichment in Tnaive cells 1 year after infection, possibly indicating that memory cells can reacquire CD45RA and CCR7 also in the absence of CD95 expression." (PMID 34875673, 2022). "After clearance of the infection, a pool of these cells settled in the GT as tissue-resident Th1 and Th17 cells expressing CD69 but not CD103, CD49d, or CCR7, where they responded rapidly to a reinfection." (PMID 31993218, 2020). "Both CTL populations were predominantly of the terminally differentiated effector memory (TEM2) phenotype, defined as CD28– CCR7– CTLs, and the frequencies of TEM2 CTLs did not change during SIVmac239 infection." (PMID 32922404, 2020). "Surprisingly, analysis of Ki-67 expression revealed that in the absence of CCR7, proliferation of both the LTi-like and NKp46+ ILC3 populations was substantially increased after infection, indicating dysregulation of the normal response to this parasite." (PMID 25575242, 2015). "In wild type mice, CCR7 is present on a subset of Tregs that do not express αE integrin (CD103), a molecule involved in the detainment of Tregs at the site of infection." (PMID 24205367, 2013).
infection (continued). "On day 7 p.i., in addition to chemokines upregulated on day 3 p.i., lethal infection further induced higher expression of CCL2, CCL6, CCL11, CCL19, CCR7, CXCR1, and CXCL11 compared to nonlethal infection." (PMID 23526993, 2013). "Regardless of infection status, NK cells were uniformly CD38+ throughout most of infancy, expressed CD45RA and lacked expression of CD28 and CCR7 (data not shown)." (PMID 23293640, 2012). "CCR7 was expressed at higher levels in the GFP+ cells than in the GFP− cells after treatment with rgHMPV or rgHPIV3, indicating that robust infection by these viruses stimulated rather than inhibited expression." (PMID 21731495, 2011). "During infection with Pru, the naive OT1GFP cells retain high levels of CCR7 and do not up regulate CCR5." (PMID 19578440, 2009). "To block CCR7-mediated trafficking of dendritic cells from the lamina propria, we treated mice with anti-VEGFR3 antibody (clone AFL4) prior to and during infection but did not see a change in dendritic numbers in the MLN as had been previously reported with other anti-VEGFR3-specific antibodies." (PMID 39714174, 2025). "While CD68 expression did not change with infection or treatment, Mtb infection resulted in the elevated expression of HLA-DR and CD200R, while activation markers such as CCR7, CD80/CD86, and CD64 as well as scavenger receptors CD163 and CD206 were reduced on Mtb-infected cells." (PMID 40305296, 2025). "The presence of CCR7 expression confers lymph node homing potential to antigen-experienced CD45RA−T cells, characteristic of central memory cells, while the absence of CCR7 allows migration to the site of infection, typical of effector cells." (PMID 39003443, 2024). "While there is evidence that upon DC activation and infection, chemokines are important to mediate T cell repositioning to DCs, our data suggests that chemokines CCL19/21 that bind to CCR7 do not play a role in T cell positioning to DCs in the absence of infection." (PMID 30093900, 2018). "LN CD16+ and DN NK cells did not express CCR7 at steady state and during MPXV infection." (PMID 24147080, 2013). "(c) CCR7+ cells might migrate to lymph nodes through nasal lymphatics, and (d) The HIV-1 viral protein U (Vpu) could downregulate CCR7, though this assumes widespread productive infection and likely does not fully account for the observed changes." (PMID 38470479, 2024).
hematological malignancies (8 papers, 2013 to 2025). "More generally, CCR7 signalling upon binding to its ligands (CCL19/21) is associated with many pro-tumorigenic effects in hematological malignancies, including migration, proliferation, survival and immune evasion." (PMID 40809150, 2024). "Currently, two clinical trials aim to validate anti-CCR7 approaches in hematologic diseases with an urgent need for more rationally based and efficient therapies." (PMID 34778050, 2021). "Anti-CCR7 mAbs have already been developed as therapeutic agents for hematologic malignancies." (PMID 40028039, 2025). "In addition, trials investigating CCR7 inhibition in patients with hematologic malignancies are ongoing." (PMID 39482533, 2024). "CCR7 promotes cell survival and proliferation in different hematological malignancies." (PMID 33110606, 2020). "We did not specifically study which signaling molecules are involved in this process, however, blocking CCR7 abrogated PI3K and ERK activation, two important components of CCR7-mediated pro-survival pathways in hematological malignancies that have shown to be relevant in T-PLL pathogenesis." (PMID 33110606, 2020). "The beneficial effects of an anti-CCR7 therapy would not be limited to the blocking of the migration of CCR7-expressing cells towards SLO but also towards different anatomic sites including CNS which represents one of the most important sanctuaries of the hematological malignancies." (PMID 24305507, 2013).